TGFBR2 (transforming growth factor beta receptor 2)
Diseases named in the same sentence as TGFBR2 in open-access papers (continued):
Sharing a sentence is not in itself a finding about the gene and the disease.
tumor (continued). "The TGFBR2 belongs to the serine/threonine protein kinase family and the TGF-β receptor subfamily, and cases of disrupted TGF-β pathway have been demonstrated to stimulate tumor progression." (PMID 31113460, 2019). "We have previously shown that TGFβ signaling and TGFβ receptor type‐2 (TGFBR2) seem to have a tumor promoting role in human estrogen receptor (ER)‐negative breast cancer." (PMID 30004628, 2018). "Concurrently, Tgfbr2 knockdown significantly increased collagen deposition in irradiated vs. non-irradiated tumours." (PMID 30504836, 2018). "In syngeneic KP tumours, Tgfbr2 knockdown did not affect non-irradiated tumour growth, but it significantly enhanced tumour growth and radiation-induced EndMT post irradiation." (PMID 30504836, 2018). "The Multiple Beam Search (MBS) algorithm learned interactions from data and discovered that hsa-miR-21, hsa-miR-10b, hsa-miR-448, and hsa-miR-96 interact with oncogenes, such as, CCND2, ESR1, MET, NOTCH1, TGFBR2 and TGFB1 that promote tumor metastasis, invasion, and cell proliferation." (PMID 28793339, 2017). "How altered TGFBR2 signaling affects exosome-mediated communication between MSI tumor cells and their environment has not been resolved." (PMID 28376875, 2017). "To determine whether Elmo1 knockdown altered tumor progression and metastasis in Tgfbr2 cKO SCC, we screened the lungs of tumor-bearing mice for YFP+ metastases by FACS." (PMID 28219480, 2017). "Furthermore, Tgfbr2 cKO lung metastases expressed YFP and contained populations of CD34+ cells, recapitulating the hierarchy of the primary tumor of origin." (PMID 28219480, 2017). "For instance, frameshift MSI events are present in TGFBR2 for 26/45 (58%) of COAD and 51/64 (80%) of STAD but only in 4/75 (5%) of UCEC cases, suggesting that certain tumour types or tumour environments are favourable to the occurrence of particular MSI events." (PMID 28585546, 2017). "Among the putative target mRNAs, they could specify known tumor genes, such as RB1 (Retinoblastoma 1, tumor suppressor) and TGFBR2 (transforming growth factor, oncogene)." (PMID 28793339, 2017). "We hypothesized that tumors arising at the anorectal transition zone in the Tgfbr2 cKO mice would contain a population of CD34-expressing cells, and that these cells would represent a population of tumor-propagating cells or so-called cancer stem cells (CSCs)." (PMID 28219480, 2017). "Up‐regulation of mRNA markers of inflammation and fibrosis have been previously reported in the fibrotic nontumor tissues 11, 45, as well as in tumor tissue in the present study (Tnf, Tgfβ1, Tgfbr1, and Tgfbr2)." (PMID 26778414, 2016). "In this system, 49 credits were assigned to poor pathological grading, 33 to reduced expression of TGFBR2, 45 to over-expression of TGF-β, 32 to over-expression of MAPK, 100 to over-expression of pin1, 50 to over-expression in tumor tissue and 22 to reduced expression of TGF-β in normal mucosa." (PMID 27008710, 2016). "At each RA concentration, the cancer cell growth outcome seems to reflect the combined effects of both the ‘absence’ of epigenetic transcriptional activation of RARA-targets (e.g. tumor suppressor functions like RARB2 and TGFBR2) and activation of PI3K kinase effectors (e.g. P-AKT)." (PMID 27894085, 2016). "Meanwhile, only one of three tumours with TGFBR2, but not ACVR2A, and one of six tumours with the reverse profile were MSI." (PMID 27302369, 2016). "We found that expression of CXCL1, but not CXCL5, decreased significantly in patients with low TGFBR2 expression, but when we analyzed subtypes of tumor we discovered significant differences only in HER2+, PR + and ER + patients." (PMID 25280532, 2014).
tumor (continued). "On the contrary, in our experimental set up WA decreased EMT-related components of the TGF-β signaling pathway (TGFA, TGFBR2, CDH11), as well as TGM2, HIF1A, several TNFSF family members and ANGPTL2, which stimulate tumor promoting pro-inflammatory responses and a hypoxic microenvironment." (PMID 24498382, 2014). "Furthermore, the predictive value increased to 0.759 considering the covariants tumor Stage (localized vs locally advanced vs distant metastases, EAU), PSA ≥ 20 ng.mL-1 at diagnosis, Gleason ≥8, TGFBR2-875GG genotype (Model 4)." (PMID 23951322, 2013). "Furthermore, TGFBR2 and EXT1 overexpression enhanced the anti-tumor effects of IFN-α/5-FU on HCC cells." (PMID 23457527, 2013). "Our result showed that MSI-high tumors were associated with indolent tumor behavior regardless of TGFBR2 or BAX mononucleotide mutation status, independent of CIMP and other key tumor molecular biomarkers." (PMID 21949851, 2011). "Specifically, we can justifiably refer to TGFBR2, ACVR2, and BAX as tumor-suppressor genes." (PMID 16417627, 2006). "The authors screened a pan-cancer tumor suppressor gene library using TGFB sensitivity as a phenotypic trait allowing for robust positive selection, and identified the transforming growth factor beta receptor 2 receptor (TGFBR2) gene as a key mediator of CRC growth." (PMID 40476002, 2025). "Blocking TGFBR2 signaling in mGSCs, through both molecular and pharmacological methods, counters this GSC-mediated immunosuppression, predicting that TGFBR2 blockades could cooperate with current immunotherapy to enhance anti-tumor effects in GBM." (PMID 40277917, 2025). "Specifically, recurrent alterations in transforming growth factor beta receptor type 2 (TGFBR2), SMAD family member 2 (SMAD2), and SMAD family member 4 (SMAD4) genes were detected, potentially impairing TGF-β signalling and underscoring the role of immune dysregulation in tumour biology." (PMID 41465261, 2025). "In the human PDAC patient tumor transcriptome (TCGA), we identify strong and significant correlations between tumoral GHR expression and known lymphangiogenic (LYVE1, FLT4, VEGFC, and PDPN) and angiogenic (PDGFRa, FGFR1, TGFB3, TGFB1, TGFBR2, HIF1a, IL6, and IL1B) markers." (PMID 39000545, 2024). "Consequently, the unique upregulation of TGF‐beta family genes TGFB1, TGFBR2, TGFBI, TGFB1I1, and TGFB3 in S‐ECM could be due to increased production of TGF‐beta by CAFs in the tumor microenvironment." (PMID 36637997, 2023). "As several lines of evidence have demonstrated the critical role of TGF-β pathway in the maintenance of tumor stemness and ALG3, another ALG family member, has recently been reported to enhance TGFBR2 glycosylation, we wondered whether ALG10 held the similar effects on TGFBR2 with ALG3." (PMID 35680565, 2022). "Due to the high expression of Tgfbr2 and LAIR-1 in MC38 tumor–infiltrating macrophages, we hypothesized that blockade of LAIR-1 signaling via NC410 could synergize with TGF-β inhibition mediated by bintrafusp alfa to remodel the myeloid cell composition of the TME." (PMID 35230974, 2022). "We detected recurrent frameshift deletions in TGFBR2 (c.374delA) and IRF2BPL (c.224_305del and c.225_303del) in ESCC, which were verified in different studies located near the N-terminal of the coding region, indicated their tumor-suppressing functions in ESCC." (PMID 36071046, 2022). "Importantly, using microdissected tumor samples and WGS, we detected the highest frequencies of homozygous deletions of the critical tumor suppressor genes CDKN2A, TGFBR2, TRAF3, and potential synthetic lethal target MTAP amongst NPC genomic reports thus far8–14." (PMID 34234122, 2021). "In the Krt8-CreERT2 model luminal tumor cells lacking Pten and Tgfbr2 de-differentiate to dual positive cells, a process that may be of interest for understanding human CaP progression." (PMID 29782499, 2018).
tumor (continued). "Besides, inactivation of TGF-β pathway by deleting TGFBR2 in combination of APC tumor suppressor deletion could result in rapid onset of invasive PCa, which implied TGFBR2 might exert tumor suppressive effect in prostate." (PMID 29699590, 2018). "Interestingly, positive correlations between the mRNA levels of TGFBR2 and the mRNA levels of TGFB1 (Spearman’s rho = 0.51, P = 5.6 × 10−5, P’ = 5.6 × 10−4) and TGFB3 (Spearman’s rho = 0.42, P = 0.0012, P’ = 0.012) were observed in the tumours (n = 59)." (PMID 26703884, 2015). "In this context, the initially described tumor-suppressive and anti-invasive properties of TRPM1 have recently been shown to be executed by its intronic miR-211 (and not by TRPM1 itself) via down-regulation of the miR-211 direct and indirect targets TGFBR2, NFAT5, and IGF2R." (PMID 24039954, 2013). "Furthermore, SCAND1 and MZF1 expression was negatively correlated with TGFBR1, TGFBR2, and TGFBR3 gene expression, suggesting that SCAND1-MZF1 could reduce TGFβ receptors to narrow down TGFβ signals emanating from the microenvironment to tumor cells." (PMID 36552758, 2022). "Therefore, such in vivo studies have demonstrated that TGFBR2 inactivation acts synergistically with other aberrant signaling pathways that are often deregulated in CRC, such as the Wnt-β-catenin, RAS-RAF, and phosphoinositol 3-kinase (PI3K) pathways, to promote tumor development." (PMID 27835699, 2016). "Upon binding with its ligand TGF-β, TGFBR2 is phosphorylated at the serine and threonine residues within its GS box, which could activate the TGF-β signaling pathway and lead to acquisition of resistance to the anti-mitogenic effects of TGF-β and contribute to tumor development and progression." (PMID 25551793, 2014). "The most significant changes in expression between sarcomatoid-tumor FOV and nonsarcomatoid-tumor FOV occurred in CD8 T cells, including downregulation of the anti-inflammatory RNA-binding protein ZFP36 (FDR < 0.001) and downregulation of TGFBR2 (FDR < 0.001)." (PMID 39639369, 2024). "After the PDX tumor was eliminated by TGFBR2-KO CAR T cells, the treated mice were re-challenged with novel contralaterally reinoculated patient-derived tumor cells, showing a persistence and antitumor properties." (PMID 33117361, 2020). "In addition, suppression of TGFBR2, but not ROCK2, led to a reduction in tumor micro-colony size at 3 weeks." (PMID 25686838, 2015). "Moreover, because we concurrently assessed clinical, pathologic and tumor molecular variables such as the CpG island methylator phenotype (CIMP), LINE-1 methylation, KRAS, BRAF and PIK3CA mutations, we could evaluate the effect of TGFBR2 or BAX mutation independent of these potential confounders." (PMID 21949851, 2011).
cancer (259 papers, 1998 to 2026). A tumor composed of atypical neoplastic, often pleomorphic cells that invade other tissues. "On the other hand, the strong association between GABPA and TGFBR2 is observed in many types of cancer based on the TCGA data analyses, which indicates a broad implication of the present findings in oncogenesis." (PMID 35549739, 2022). "Further, models with cancer cells bearing Tgfbr2 mutations showed an increased immune infiltration when treated with a TGFβ-R2 inhibitor, thereby depleting TGFβ signalling in stromal cells only." (PMID 34638468, 2021). "Studies concerning sporadic endometrial carcinoma revealed a silent polymorphism (AAC→AAT) at codon 389 in the TGFBR2 gene in 44% of analyzed cancer cases." (PMID 34501347, 2021). "To better understand their role in the susceptibility and clinical features of thyroid cancer, we analyzed some TGFB1, TGFBR1, and TGFBR2 SNPs previously associated with human cancers as well as SNPs that have been implicated on gene and protein deregulation." (PMID 33905626, 2021). "The SNVs with G:C to T:A transversion- or G:C to A:T transition-containing genes included cancer-associated genes such as Tgfbr2 and Tusc3." (PMID 34912374, 2021). "In mouse models, deletion of the Apc gene in mouse prostate epithelium results in HGPIN, which rapidly progresses to invasive cancer when combined with loss of the Tgfbr2 gene." (PMID 29782499, 2018). "Variants in the TGFBR2 kinase domain cause several human diseases and can increase propensity for cancer." (PMID 28182693, 2017). "The TGFBR2 gene is a common target for microsatellite-unstable and microsatellite-stable mutations, which can induce cancer progression." (PMID 28195144, 2017). "Compared with high expression of TGFBR2, low expression of TGFBR2 was associated with a higher incidence of cancer-related death (HR = 1.70) and poor outcomes (P = 0.034)." (PMID 28195144, 2017). "As loss of PTEN and TGFBR2 from prostate has been shown to result in castration-resistant cancer with metastases, we assume that miR-216a would play a critical role in the modulation of AR signaling and development of endocrine resistance." (PMID 26506397, 2015). "The TGFBR2 locus was shown to be mutated in the 10-adenine (A10) tract of exon 3 and serine-threonine kinase domain in some cancers." (PMID 27462425, 2015). "The downregulation of TGFBR2 expression in cancer cells can be caused by multiple mechanisms, including hypermethylation of the TGFBR2 promoter and, as we show here, through miRNA regulation." (PMID 24606633, 2014). "Both ACVR2 and TGFBR2 mutations commonly occur simultaneously in MSI cancers, and cell lines also can lose both TGFβ and activin signaling." (PMID 22761777, 2012). "Notably, TGF-Beta pathway genes such as SMAD2, SMAD4, and TGFBR2 displayed differential mutation frequencies in all three cancers, suggesting a recurring pattern of dysregulation in this pathway among H/L patients." (PMID 40869017, 2025). "However, the molecular mechanism of cancer cells‐intrinsic Tgfbr2 loss promoting desmoplastic reaction in NPC is unclear." (PMID 39049720, 2024). "Eight targets (EP300, CASP3, CASP8, CHEK2, CREBBP, NOTCH1, PPARG, and TGFBR2) were TSGs (gray text), suggesting that antagonizing these molecules might increase the susceptibility to cancer in healthy individuals." (PMID 37888486, 2023). "However, various mutations were detected in other genes such as Tusc3 and Tgfbr2, which have been reported as cancer-associated or homeostatic squamous cell genes." (PMID 34912374, 2021). "DCs isolated from healthy donors were successfully depleted for Rab7b, loaded with a specific cancer peptide (a TGFBR2 frameshift mutation-derived epitope), and further incubated with autologous T cells transfected with the validated cognate T cell receptor (TCR), Radium-1." (PMID 34494097, 2021). "Downregulation or missense mutation of TGFBR2 has been found in several cancers." (PMID 32046777, 2020).
cancer (continued). "Additionally, evidence from recent studies has shown that cancer development can be affected by mutations in the TGFβII receptor (TGFBR2), SMAD4, and activin receptor 2A (ACVR2A)." (PMID 31906017, 2019). "TGFBR2 mutation in CRC can also cause changes in the components secreted by cancer cells." (PMID 31756952, 2019). "In addition we observed increased numbers of basal cells, which make up much of the invasive cancer, and we show that loss of Tgfbr2 primarily affects basal cell proliferation." (PMID 29782499, 2018). "Thus, the combination of a local micro-invasive phenotype initiated by Pten loss, together with increased proliferation due to loss of Tgfbr2 drives rapid progression to invasive cancer." (PMID 29782499, 2018). "Underexpression or mutation of TGFBR2 is found in a number of cancers except cervical cancer." (PMID 28195144, 2017). "Furthermore, patients with TGFBR2low/hTERThigh had a higher incidence of cancer-related death (HR = 1.892), while the risk of patient death with only high expression of hTERT or low expression of TGFBR2 was lower (HR = 1.390 and 1.704, respectively)." (PMID 28195144, 2017). "To date, the cellular and molecular mechanisms of Tgfbr2-deficient transition zone carcinoma development and metastasis are unknown." (PMID 28219480, 2017). "Loss of TGFBR2 expression enables cancer cells to escape the growth inhibitory effect of TGF-β and may cause loss of cell growth regulation." (PMID 27120811, 2016). "Furthermore, TGFBR2 is a frequent locus of inactivating mutations, and the mechanism of TGFBR2 dysregulation vary among different cancers." (PMID 27120811, 2016). "Analysis of the mechanism underlying TGFBR2 loss may provide clinical value for the identification of new therapeutic targets and approaches for certain subsets of cancer." (PMID 26061281, 2015). "In GG homozygous carriers, the lower expression levels of TGFBR2 may be associated with cellular disruptions in the TGFβ1 signaling pathway and induces the acquisition of aggressive cancer phenotypes." (PMID 23951322, 2013). "Silencing TGFBR2 in cancer cells or treating with anti-TGFBR2 antibodies mitigated CD8 T cell exhaustion thereby highlighting the pivotal role of TGFBR2." (PMID 41872131, 2026). "To support their possible roles in crucial oncogenic mechanisms, we assessed the mutation frequency, copy number amplification, and copy number–expression correlation of STC2, MIF, CD74, CXCR4, GDF15, and TGFBR2 across several cancer types." (PMID 41502509, 2025). "The distinct roles of TGFBR1 and TGFBR2 in cancer, especially as they pertain to immune regulation in GBM, remain undetermined." (PMID 40277917, 2025). "The co-receptor-dependent targeting of TGFBR2 by the parasite provides a template for the development of therapies for targeting the cancer- and fibrosis-promoting activities of the TGF-βs in humans." (PMID 39984487, 2025). "Together, these results identified the TGFBR2-induced signature of immunosuppressive effector genes, known to be expressed by Tregs, in mesenchymal cancer cells across multiple solid tumor types." (PMID 40277917, 2025). "Impaired TGFβ signaling, caused by reduced TGFBR2 expression in CAFs, leads to increased secretion of HGF, further contributing to cancer progression (TGFB-HGF axis)." (PMID 40075643, 2025). "Our results indicated that the phosphorylation of STAT1 activated by TGFBR2 fulfilled a cancer-suppressing function in BC." (PMID 39525474, 2024). "We found that the abundance of either the type I (TGFBR1) or type II (TGFBR2) TGF-β receptor determined the responses of cancer cell lines, such that the receptor with relatively low abundance dictates the response." (PMID 38753874, 2024). "This robust correlation supports the likelihood of imbalanced protein expression of TGFBR1 and TGFBR2 in cancer cell lines." (PMID 38753874, 2024).